ALOX5AP (arachidonate 5-lipoxygenase activating protein)
Diseases named in the same sentence as ALOX5AP in open-access papers (continued):
Sharing a sentence is not in itself a finding about the gene and the disease.
alopecia (1 paper, 2013). Hair loss usually from the scalp. "In the GWAS of the CEF-treated group, genetic variants in the ALOX5AP gene on chromosome 13 were most significantly associated with chemotherapy-induced alopecia (rs3885907, minimum P = 1.38 × 10-6, OR = 2.66, 95% CI: 1.71 to 4.13)." (PMID 24025145, 2013). "Detailed biological mechanisms in hair growth cycle are not well characterized, but one paper reported involvement of the ALOX5AP upregulation in scarring alopecia." (PMID 24025145, 2013).
apical periodontitis (1 paper, 2022). "During apical periodontitis development, synthesis of genes that encode 5-LO (Alox5) and 5-lipoxygenase activating protein (FLAP; Alox5ap) were upregulated at 14 days (p <0.05) and down regulated latter on (p <0.05)." (PMID 36287497, 2022).
chronic myeloid leukemia (1 paper, 2019). "Of note, among genes deregulated in the leukotriene pathway we identified ALOX5 (fold change = −4.36) and ALOX5AP (fold change = −2), where the loss of ALOX5 has been reported to impair leukemic stem cells and prevent the onset of chronic myeloid leukemia in mice." (PMID 31817495, 2019).
diffuse large B-cell lymphoma (1 paper, 2023). "ALOX5AP expression was higher in tumor tissues than in normal tissues from glioblastoma multiforme (GBM), lymphoid neoplasm diffuse large B-cell lymphoma (DLBC) and AML." (PMID 37994961, 2023).
hyperlipidemia (1 paper, 2025). "Notably, metabolic DEGs such as ACSL1, ABCA1, ABCG1, ACAT2, ALOX5AP, PLA1A, and PPARG were elevated in hyperlipidemia." (PMID 39853712, 2025).
liver fibrosis (1 paper, 2021). "Furthermore, we demonstrated that single cell sequencing helps identifying novel, cell-specific markers such as COL15A1, ALOX5AP, and LAPTM5 that could further improve our understanding of liver fibrosis." (PMID 33922101, 2021).
malaria (1 paper, 2023). Malaria is a serious and sometimes fatal disease caused by a parasite that commonly infects a certain type of mosquito which feeds on humans. "Within innate myeloid cells, malaria drove changes to monocytes consistent with the induction of immunosuppressive MS1-like monocytes, which have high expression of alarmins S100A8/A9, along with RETN and ALOX5AP and reduced expression of MHC class II." (PMID 37968278, 2023).
melanoma (1 paper, 2022). A malignant, usually aggressive tumor composed of atypical, neoplastic melanocytes. "Based on the FAM molecular subtypes, we identified the 6 FAMGs (ACSL5, ALOX5AP, CD1D, CD74, IL4I1, TBXAS1) that play vital regulatory roles in the melanoma TME." (PMID 36466837, 2022).
monocytic leukemia (1 paper, 2023). "Combined with the previous mention, the expression of ALOX5AP is significantly increased in monocytic leukemia (M4 and M5 subtypes according to FAB classification), does ALOX5AP play a more specific and significant role in monocytic leukemia, which needs further confirmation." (PMID 37994961, 2023). "Moreover, ALOX5AP expression was significantly higher in monocytic leukemias (M4 and M5 subtypes according to FAB classification)." (PMID 37994961, 2023).
myeloid leukemia (1 paper, 2025). A clonal proliferation of myeloid cells and their precursors in the bone marrow, peripheral blood, and spleen. "Whereas, the ALOX5AP rs10507391 SNP was reported to increase susceptibility to myeloid leukemia in Chinese population." (PMID 40737279, 2025). "Moreover, the ALOX5AP gene polymorphisms were reported to be associated with thyroid cancer, myeloid leukemia and Alzheimer’s disease." (PMID 40737279, 2025).
ocular hypertension (1 paper, 2024). Abnormally high intraocular pressure. "The results demonstrate that Alox5AP (5-lipoxygenase activating protein, FLAP), which is a cofactor required for full 5-LOX enzymatic activity, was significantly upregulated at 2 and 4 weeks, while there was no change in the levels of Alox5 in response to ocular hypertension." (PMID 38610040, 2024).
ovarian adenocarcinoma (1 paper, 2021). An adenocarcinoma that arises from the ovary. "To further verify these results, we utilized the DepMap database to explore ALOX5AP expression and cisplatin sensitivity of 12 ovarian adenocarcinoma cell lines." (PMID 34094977, 2021).
renal fibrosis (1 paper, 2025). A final common manifestation of a wide variety of chronic kidney diseases characterized by glomerulosclerosis and tubulointerstitial fibrosis. "We found that ALOX5AP exhibited the most significant differential expression and was associated with the promotion of renal fibrosis, with a fold change greater than 1 and p < 0.05, suggesting that ALOX5AP is a key pathway gene." (PMID 40995682, 2025). "Consistent with the mRNA levels, the protein levels of ALOX5AP were significantly elevated in the kidney tissues of NAFLD mice with renal fibrosis." (PMID 40995682, 2025). "Thus, the ANGPTL8/PIRB/ALOX5AP axis is a crucial signaling pathway between the liver and kidneys, and CCR2+PIRB+ macrophages play a pivotal role in the progression of NAFLD‐induced renal fibrosis." (PMID 40995682, 2025). "Given the significant correlation between NAFLD and renal fibrosis, we propose the central hypothesis that ANGPTL8 derived from NAFLD activates the ALOX5AP pathway in renal CCR2+PIRB+ macrophages via PIRB, reprogramming linoleic acid metabolism, and driving profibrotic inflammation." (PMID 40995682, 2025).
thyroid cancer (1 paper, 2023). "For example, one study reported that genetic variants of ferroptosis‐related APOE, BCL3, and ALOX5AP were associated with the risk of thyroid cancer." (PMID 38151984, 2023).
tumor (26 papers, 2007 to 2026). "Genes specifically upregulated in the high mRNAsi group included MKI67, MGST1, and ALOX5AP, which are associated with lipid metabolism, endoplasmic reticulum stress, and tumor progression." (PMID 40963856, 2025). "Second, the expression of 5-lipoxygenase activating protein (ALOX5AP), a regulator of tumor immunity associated with “hot” tumors, was a distinguishing characteristic between mice infected HTLV-1-CTCF-A and HTLV-1-p12stop." (PMID 40460345, 2025). "Second, the expression of 5-lipoxygenase activating protein (ALOX5AP), a regulator of tumor immunity associated with “hot” tumors, was a distinguishing characteristic between mice infected HTLV-1-CTCF-2 and HTLV-1-p12stop." (PMID 38853836, 2024). "An increased expression of ALOX5AP (arachidonate 5-lipoxygenase activating protein) was associated with both increased M2 macrophages in the tumor microenvironment and a poorer patient prognosis." (PMID 35565348, 2022). "The ALOX5AP inhibitor zileuton has been shown to decrease tumor-associated macrophage (TAM) infiltration in murine models, while targeting TREM2 and TYROBP may reverse immunosuppression." (PMID 40438577, 2025). "In addition, the results of ROC assays confirmed the diagnostic value of ALOX5AP in screening OS specimens from non-tumor specimens with AUC = 0.8717." (PMID 37344882, 2023). "As subpopulations of tumour-associated immune cells expressed ALOX5AP and ALOX5 (encoding the enzymes that catalyse the leukotriene synthesis), the ligand for wild-type CysLT2R may be produced by immune cells in the inflammatory microenvironment." (PMID 33588787, 2021). "Pseudotime trajectory analysis positioned OxP-Mac as an early-state population branching into tumor-specific subsets (ALOX5AP+, HERPUD1+ and PRDX1+LA-Mac), suggesting differentiation plasticity." (PMID 41601657, 2026). "Among the identified five distinct macrophage subpopulations (FCN1+Inflam-Mac, PRDX1+LA-Mac, HERPUD1+LA-Mac, ALOX5AP+LA-Mac and OxP-Mac), OxP-Mac predominantly enriched in normal kidney tissues, whereas the other subtypes were mainly found in tumor regions." (PMID 41601657, 2026). "ALOX5AP was expressed in all of the major macrophage subpopulations, indicating broad activity in tumor-infiltrating macrophages." (PMID 41164132, 2025). "The qRT-PCR results, based on 15 clinical GBM and paired non-tumor brain tissue samples, showed that the mRNA levels of ALOX5AP, LGALS1, and PLA2G5 were significantly higher in GBM tumor tissues compared to non-tumor brain tissues (all p < 0.05)." (PMID 41164132, 2025). "We evaluated the relationship between ALOX5AP expression and tumor-infiltrating immune cells in the AML microenvironment in the TCGA database using the CIBERSORT algorithm." (PMID 37994961, 2023). "The expression of ALOX5AP was distinctly downregulated in OS specimens compared with non-tumor specimens." (PMID 37344882, 2023). "Then, we performed RT-PCR to examine the expression of ALOX5AP in 30 pairs of OS specimens and matched non-tumor specimens." (PMID 37344882, 2023). "Expression of ALOX5AP was shown to be significantly lower in OS samples compared to non-tumor controls by RT-PCR." (PMID 37344882, 2023). "In functional assays, we confirmed that ALOX5AP served as a tumor suppressor in OS via regulating Wnt/β-catenin pathway." (PMID 37344882, 2023). "In this scenario, the pivotal expression and methylation levels of ALOX5AP strongly indicate a relevant role of arachidonic acid-containing phospholipids and the derived metabolism in the tumor microenvironment and GBM progression." (PMID 35328369, 2022). "Overall, our results suggest that ALOX5AP is involved in the immune regulation of tumor microenvironment of SOC." (PMID 34094977, 2021). "A predictive nomogram, which integrated ALOX5AP expression and two independent prognosis factors (primary therapy outcome and tumor residual), was conducted to predict the 3-year and 5-year survival rate of SOC patients." (PMID 34094977, 2021).
tumor (continued). "The expression of C3 allows their involvement in complement activation within the tumor microenvironment, thereby influencing tumor cell lysis and immune cell activation.ALOX5AP and LTC4S participate in arachidonic acid metabolism, modulating inflammatory responses and immune cell functions." (PMID 41394809, 2025). "ALOX5AP promotes tumor progression by influencing the tumor microenvironment, specifically by driving M2 macrophage polarization, which supports immunosuppression and tumor growth." (PMID 40330466, 2025). "All these data suggested that ALOX5AP was closely related to tumor immune infiltration." (PMID 37994961, 2023). "In this study, we also examined whether ALOX5AP exhibited its tumor-suppressive roles via regulating Wnt/β-catenin pathway." (PMID 37344882, 2023). "Additionally, ALOX5AP was enriched in the C4 (lymphocyte depleted) immune subtype of SOC and associated with crucial immune-repressive receptors in the tumor microenvironment at the genomic level." (PMID 34094977, 2021). "Furthermore, ALOX5AP overexpression led to dramatically reduced tumor weights." (PMID 37344882, 2023). "Consistently, Western blot analysis confirmed markedly up-regulated protein expression of ALOX5AP and LGALS1 in GBM tumors versus non-tumor tissues." (PMID 41164132, 2025). "In contrary, those cells performing anti-tumor responsiveness (i.e., activated CD4 T cells, effector memory CD4 T cells, and CD8 T cells) were significantly negatively correlated ALOX5AP expression (P < 0.001)." (PMID 37994961, 2023). "In a similar number of tumor types, there is a reduction in the expressions of 5-LOX/ALOX5 and FLAP/ALOX5AP." (PMID 36765904, 2023). "Mean expression levels of COX1, COX2, ALOX5, ALOX5AP and correlated genes of the JAK STAT and Src pathways in adjacent tissues were similar to levels in the tumor samples." (PMID 37190308, 2023). "• A functional antitumor response, intra-tumor cell retention (ITGAE, ITGA1, etc.) and tumor residency (ALOX5AP, CXCL13, etc.) similar to CD39+CD8+T cells.• Expressed activation/co-stimulation genes to resist exhaustion." (PMID 36451828, 2022). "Meanwhile, the elevated methylation of ALOX5AP in the Proneural subtype and its lower methylation in the Mesenchymal suggest the involvement of the eicosanoid metabolism in stromal cells, which could account for tumor microenvironment enrichment in arachidonic acid." (PMID 35328369, 2022). "ALOX5AP participates in SOC progression via M2 macrophage recruitment and polarization as well as mediating immune suppression in the tumor immune microenvironment." (PMID 34094977, 2021). "Drugs that inhibit fatty acid oxidation or interfere with lipid signaling pathways, such as inhibitors of ALOX5AP or FABP5, could serve as potential therapies for GBM by impairing the metabolic fitness of TAMs and reactivating anti-tumor immunity." (PMID 41164132, 2025). "Though ALOX5AP is primarily found in haematopoietic cells, aberrant expression of ALOX5AP has been detected in numerous tumor cells of non-myeloid origin, with important prognostic significance." (PMID 34094977, 2021).
cancer (17 papers, 2013 to 2025). A tumor composed of atypical neoplastic, often pleomorphic cells that invade other tissues. "To elucidate the association between ALOX5AP and immune regulation, we analyzed ALOX5AP correlation to multiple immune inhibitors across 33 TCGA cancer types." (PMID 34094977, 2021). "Prior research also suggests widespread expression of ALOX5AP in 20 different types of epithelial cancer cell lines, implicating its potentially crucial role in influencing cancer patient prognosis." (PMID 39108264, 2024). "Although ALOX5AP has been reported to possess important prognostic significance in several cancer types, including serous ovarian cancer, thyroid cancer, lung adenocarcinoma, and glioma." (PMID 37994961, 2023). "The overexpression of ALOX5AP has been observed in many types of cancer and has been identified as an oncogene." (PMID 37994961, 2023). "Last, to better understand the clinical relevance of ALOX5AP in multiple human cancers, we compared ALOX5AP mRNA levels across 33 TCGA cancer types and matched GTEx normal controls." (PMID 34094977, 2021). "Previous studies have found that the 5-LOX/ALOX5AP pathway plays important roles in manipulating the TME by affecting cancer-related immune evasion." (PMID 34094977, 2021). "Among Black women, an increased risk of ER+ cancer was observed for ALOX5-rs1369214 (OR: 1.53, 95% CI: 1.15–2.03) and ALOX5AP-rs9579648 (OR: 2.36, 95% CI: 1.15–4.84) in the recessive models." (PMID 34249719, 2021). "Due to the complexity of immunoregulation in cancer pathogenesis and progression, the exact molecular mechanisms of ALOX5AP in mediating immune response remain to be fully elucidated." (PMID 34094977, 2021). "ALOX5AP has been reported to possess important prognostic significance in several cancer types, including colorectal cancer, lung adenocarcinoma, low-grade glioma, and osteosarcoma." (PMID 34094977, 2021). "As shown, ALOX5AP mRNA in lung, liver, breast, peritoneum, and lymph node tissues displayed higher levels than in the matched cancer tissues." (PMID 31992246, 2020). "Furthermore, given that immune checkpoints are promising therapeutic targets for cancer therapy, we also evaluated the relationship between ALOX5AP and the set of checkpoint genes." (PMID 37994961, 2023). "This conserved expression suggests that ALOX5AP may have a fundamental role in mediating cancer development." (PMID 34094977, 2021). "Three candidate genes (ALOX5AP, CD74, and FCGR2A) were found, all of which were expressed at higher levels in lungs and lymph nodes than in matched cancer tissues and were probably expressed in the microenvironment." (PMID 31992246, 2020). "Further evidence of the pro-cancer role and negative prognostic significance of ALOX5AP in haematological diseases." (PMID 37994961, 2023).
infection (6 papers, 2017 to 2025). The state of being infected such as from the introduction of a foreign agent such as serum, vaccine, antigenic substance or organism. "We found that, after infection, immature C57BL/6 mice showed increased lung cysLT levels and rare Alox5+ and Alox5ap+ cells in the airway epithelium with a triangular or bottle-like shape typical of tuft cells." (PMID 41573550, 2025).
neurologic disease (1 paper, 2019). "We chose Alox5ap and Laptm5 to illustrate that expression profiles for the microglial gene module were similar irrespective of whether a gene has an established role in neurologic disease (e.g., Trem2 and Alox5ap) or limited to no known role (e.g., Laptm5) in neurologic disease." (PMID 31214167, 2019).
ALOX5AP also shares sentences with these, for which no sentence is quoted: lung carcinoma (10 papers); cardiovascular disease (3); amyloidosis (2); Anxiety (2); Arthritis (2); breast tumor (2); colon cancer (2); hepatocellular carcinoma (2); liver cancer (2); lung adenocarcinoma (2); periodontitis (2); peripheral arterial disease (2); prostate carcinoma (2); type 2 diabetes (2); acute monoblastic/monocytic leukemia (1); age-related macular degeneration (1); Allergy (1); autism (1); carotid atherosclerosis (1); Cerebral ischemia (1); cerebrovascular diseases (1); cognitive decline (1); cognitive deficits (1); depression (1); diabetic nephropathy (1); ductal adenocarcinoma (1); esophageal carcinoma (1); familial hypercholesterolemia (1); fatty liver disease (1); gastric cancer (1).
A further 24 diseases each share a sentence with ALOX5AP in 1 paper.